MOBP (myelin associated oligodendrocyte basic protein)
Description:
May play a role in compacting or stabilizing the myelin sheath, possibly by binding the negatively charged acidic phospholipids of the cytoplasmic membrane.
Tractability: No criterion of Open Targets' tractability assessment is met for any kind of drug.
Gene: Protein-coding gene on chromosome 3 (39,467,172 to 39,529,479, forward strand). Ensembl gene ENSG00000168314.
Subcellular location: Cytoplasm, perinuclear region
Subcellular location (Human Protein Atlas): Cytoplasmic bodies
Gene Ontology:
Molecular function: protein binding; structural constituent of myelin sheath
Biological process: nervous system development
Cellular component: cytoplasmic ribonucleoprotein granule; mitochondrion; perinuclear region of cytoplasm
Genetic constraint (gnomAD): Loss-of-function variants: 4 observed, 14.1 expected, observed/expected ratio (o/e) 0.28, 90% interval 0.14 to 0.65. The upper end of that interval is the gene's LOEUF score, 0.65, which puts it in group 2 of 6, group 1 being the genes least tolerant of losing a copy. Missense variants: 156 observed, 237.32 expected, observed/expected ratio (o/e) 0.66, 90% interval 0.58 to 0.75. Synonymous variants: 72 observed, 90.92 expected, observed/expected ratio (o/e) 0.79, 90% interval 0.65 to 0.96.
Homologues: Orthologues: chimpanzee MOBP (99% identical), macaque MOBP (90% identical), dog MOBP (77% identical), mouse Mobp (76% identical), rat Mobp (76% identical), zebrafish myripb (37% identical), tropical clawed frog myrip (34% identical), zebrafish myripa (32% identical). Paralogues in human: MYRIP (38% identical), MLPH (21% identical).
Diseases named in the same sentence as MOBP in open-access papers:
MOBP is named in the same sentence as 36 diseases in open-access papers, as found by Europe PMC text mining. Sharing a sentence is not in itself a finding about the gene and the disease. The quoted sentences say what the papers report.
corticobasal degeneration (6 papers, 2018 to 2022). "Moreover, MOBP rs1768208 has been independently identified as a risk factor in confirmed cases of corticobasal degeneration (DCB) and in cases of PSP." (PMID 36071893, 2022). "Genetic variants in the MOBP gene have been previously associated with neurodegenerative diseases, including PSP and corticobasal degeneration, in which genetic variants in this gene associate with the disease risk." (PMID 33368549, 2021). "Myelin-Associated Oligodendrocyte Basic Protein (MOBP) has been associated with progressive supranuclear palsy (PSP), corticobasal degeneration (CBD), frontotemporal dementia (FTD) and LOAD." (PMID 29425116, 2018). "This revealed a shared signal in the MOBP–RPSA locus between ALS, PSP and corticobasal degeneration (CBD) as well as a shared signal in the UNC13A locus between ALS and FTD (posterior probability, PPH4 > 95%)." (PMID 34873335, 2021).
multiple sclerosis (5 papers, 2005 to 2024). A progressive autoimmune disorder affecting the central nervous system resulting in demyelination. "For example, myelin-associated oligodendrocyte basic protein (MOBP) is implicated as an antigen stimulus for multiple sclerosis, a disease that also can present with optic neuritis." (PMID 16168081, 2005). "Also, proteins encoded by human orthologs of PLP1, MBP, and MOBP are known to be antigens recognized by CD4+ T cells in multiple sclerosis patients." (PMID 36817487, 2023). "More recent work implicates MOBP with other myelin proteins as primary antigens in the autoimmune response in multiple sclerosis." (PMID 24503276, 2014).
frontotemporal dementia (4 papers, 2018 to 2024). Frontotemporal dementia (FTD) comprises a group of neurodegenerative disorders, characterized by progressive changes in behavior, executive dysfunction and language impairment, as a result of degeneration of the medial prefrontal and frontoinsular cortices. "The MOBP gene is thought to be involved in both frontotemporal dementia and nervous system development." (PMID 36768488, 2023).
Alzheimer disease (3 papers, 2021 to 2024). A progressive, neurodegenerative disease characterized by loss of function and death of nerve cells in several areas of the brain leading to loss of cognitive function such as memory and language. "According to the GWAS catalog, the MOBP gene, which is a myelin-associated oligodendrocyte-associated protein, is linked to Alzheimer’s disease, cognitive performance, and other brain-related disorders." (PMID 36768488, 2023).
depression (3 papers, 2011 to 2024). "Decreased levels of MAG, MAL, CNPase, and MOBP, were also confirmed in animal models of depression and in the human postmortem study in depressed patients." (PMID 38235150, 2023). "PEBP1 has been suggested to be involved in chronic stress-induced memory impairment, MOBP has been linked to mood disorders, LTA4H to depression in women, and KCNN2 to anxiety and stress responses." (PMID 21504592, 2011).
schizophrenia (3 papers, 2012 to 2017). A major psychotic disorder characterized by abnormalities in the perception or expression of reality. "In addition, mRNA levels of myelin-associated oligodendrocyte basic protein (MOBP), an oligodendrocyte-associated gene, are increased in Pfc white matter in schizophrenia patients." (PMID 29163023, 2017).
tauopathy (3 papers, 2015 to 2025). Neurodegenerative disorders involving deposition of abnormal tau protein isoforms (tau proteins) in neurons and glial cells in the brain. "Given the significant white matter and oligodendrocyte pathology in these primary tauopathies, the genetic association with MOBP warrants functional characterization to determine its role in CBD and PSP." (PMID 26077951, 2015). "For example, MOBP, a tauopathy risk gene, was strongly correlated with tau in PiD (ρ = 0.82; p‐value = 0.004) but not in CBD (ρ = 0.0; p‐value = 0.94) or PSP (ρ = −0.61; p‐value = 0.06), suggesting tauopathy risk genes are partitioning in solubility differently in each disease." (PMID 40545554, 2025). "In the present study, MOBP protein levels did distinguish MSA from PSP and HD, two diseases of the tauopathy spectrum." (PMID 33368549, 2021).
amyotrophic lateral sclerosis (2 papers, 2021 to 2025). Amyotrophic lateral sclerosis (ALS) is a neurodegenerative disease characterized by progressive muscular paralysis reflecting degeneration of motor neurons in the primary motor cortex, corticospinal tracts, brainstem and spinal cord. "Background and Objectives: To date, only one study has investigated the association between the rs616147 polymorphism of the Myelin-associated Oligodendrocyte Basic Protein (MOBP) locus and Amyotrophic Lateral Sclerosis (ALS)." (PMID 34946282, 2021). "One study investigated the rs616147 polymorphism of the myelin-associated oligodendrocyte basic protein (MOBP) gene as a possible risk factor for PD, building on its known association with amyotrophic lateral sclerosis (ALS)." (PMID 40364031, 2025).
dementia (2 papers, 2021). Loss of intellectual abilities interfering with an individual's social and occupational functions. "To date, autoreactivity against MOBP has been detected among individuals with MS and MOBP immunoreactivity has been detected in the core of Lewy Bodies (LBs) among patients with Parkinson’ s disease and dementia with LBs." (PMID 34946282, 2021).
Dementia with Lewy Bodies (2 papers, 2020 to 2021). "Interestingly, a study aiming to identify common DNA methylation changes across neurodegenerative diseases has shown shared changes in HIP1 (AD and Down syndrome) and MOBP (PD and Dementia with Lewy Bodies)." (PMID 31535203, 2020).
acute disseminated encephalomyelitis (1 paper, 2025). Acute disseminated encephalomyelitis (ADEM) is a demyelinating disorder of the central nervous system. "In a microarray assay assessing antibody reactivity against a broad spectrum of antigens to differentiate MS from acute disseminated encephalomyelitis (ADEM), the presence of anti-MOBP IgG was more indicative of ADEM than of MS, which parallels findings on MOG antibodies." (PMID 41226806, 2025).
autism (1 paper, 2021). Persistent deficits in social interaction and communication and interaction as well as a markedly restricted repertoire of activity and interest as well as repetitive patterns of behavior. "The level of myelin-associated oligodendrocyte basic protein was decreased and was associated with the presence of autism-related symptoms." (PMID 34576223, 2021).
cocaine abuse (1 paper, 2023). Disorders related or resulting from use of cocaine. "In addition, MOBP has already been implicated in cocaine abuse." (PMID 37433118, 2023).
demyelinating disease (1 paper, 2014). A broad group of disorders that affect the myelin sheaths that cover the neurons. "We suggest that increased mRNA levels of ARE-containing myelin proteins (MBP, MOBP) resulting from EXOSC8 deficiency initiate a cascade of downstream events, and the disturbed balance between ARE and non-ARE myelin components results in demyelinating disease." (PMID 24989451, 2014).
encephalomyelitis (1 paper, 2021). Inflammation of the brain and the spinal cord. "High MOBP expression is significantly associated with the occurrence of encephalomyelitis." (PMID 34516348, 2021).
glioma (1 paper, 2023). A benign or malignant brain and spinal cord tumor that arises from glial cells (astrocytes, oligodendrocytes, ependymal cells). "In IDH-mutant/PM gliomas, coordinated hypermethylation in the transcription start site (TSS)/CpG island regions was observed in MO marker (GALC/O1), myelin components (MAG, MBP, MOBP, MOG), and essential regulators of the myelination program (MYRF/C11orf9 and SOX10)." (PMID 37055795, 2023).
Huntington disease (1 paper, 2021). Huntington disease (HD) is a rare neurodegenerative disorder of the central nervous system characterized by unwanted choreatic movements, behavioral and psychiatric disturbances and dementia. "Although soluble protein levels for MOBP and HIP1 in cerebellar white matter were not significantly different between MSA cases and controls, we found striking differences between MSA and other neurodegenerative diseases, including PD and Huntington's disease." (PMID 33368549, 2021).
lung carcinoma (1 paper, 2021). "Interestingly, MOBP was upregulated in male smokers with lung cancer." (PMID 34516348, 2021).
optic disc oedema (1 paper, 2023). "MOBP (myelin-associated oligodendrocyte basic protein), thought to be involved in stabilisation of the myelin sheath, occupied a clade enriched for astrocyte projection, spinal cord injury, and optic disc oedema." (PMID 36766730, 2023).
Timothy syndrome (1 paper, 2023). "Similar to the Timothy syndrome mouse model, we found that loss of FOXP1 specifically in iSPNs enhanced the maturation of oligodendrocytes and significantly increased the mature oligodendrocyte marker MOBP in adult striatum." (PMID 37270616, 2023).
neurodegenerative disease (5 papers, 2020 to 2026). A disorder of the central nervous system characterized by gradual and progressive loss of neural tissue and neurologic function. "Myelin oligodendrocyte basic protein (MOBP) is an abundant oligodendrocyte gene implicated in multiple neurodegenerative diseases." (PMID 41929081, 2026). "OLG-related genes (e.g. MOBP and BIN1) have been associated in GWAS with the risk of developing neurodegenerative diseases." (PMID 37386505, 2023). "Our data provide the first evidence for changes in DNA methylation across brain regions in MSA, including in HIP1, LMAN2 and MOBP, all relevant to neurodegenerative diseases." (PMID 31535203, 2020). "Our results suggest that HIP1 and, to some extent MOBP, may be candidate markers in neurodegenerative diseases." (PMID 33368549, 2021).
cancer (2 papers, 2020 to 2021). A tumor composed of atypical neoplastic, often pleomorphic cells that invade other tissues. "However, the molecular mechanism of MOBP in cancers, including GBM, remains unknown." (PMID 34516348, 2021). "Genes and AS events enrolled in the comprehensive prognostic signature included RHOT1 (ES), SH3KBP1 (AP), AGTRAP (AA), PACS2 (AP), RBPMS (AT), B3GNTL1 (AP), MOBP (AT), NPHP3 (ES), ABCC5 (RI), FKTN (ES) and FKBP8 (AA), many of which are known to play important roles in cancer biology." (PMID 32467664, 2020).
neurological diseases (2 papers, 2005 to 2022). "These genes include MOBP (an oligodendroctye and white matter marker), PCP4 (associated with L5 and L6) and GFAP (associated with astrocytes and many neurological disorders)." (PMID 35380614, 2022). "Both signatures included a number of genes (MBP, MOBP, MAG, OLIG1, and OLIG2) previously found in glial cells, several of which have been linked to neurological diseases." (PMID 16168081, 2005).
brain diseases (1 paper, 2024). "It was found that MOBP expression is downregulated in SAMP8 mice, potentially playing a role in age-related brain diseases." (PMID 38979414, 2024).
MOBP also shares sentences with these, for which no sentence is quoted: progressive supranuclear palsy (4 papers); multiple system atrophy (3); Down syndrome (2); Parkinson disease (2); Anxiety (1); infection (1); memory impairment (1); mood disorder (1); oligodendroglioma (1); optic neuritis (1); synucleinopathies (1); tumours (1).